LRP1 (LDL receptor related protein 1)
Diseases named in the same sentence as LRP1 in open-access papers (continued):
Sharing a sentence is not in itself a finding about the gene and the disease.
breast carcinoma (continued). "Interestingly, tumor cell lines such as breast cancer, ovarian cancer, and melanoma do express LRP1, though at different levels, confirming that the relationship between expression of LRP1 and cancer development is complicated." (PMID 37020553, 2023). "In addition, fibronectin and eHSP90 have been found to co-localize in a common complex with LRP1 on the surface of breast cancer cells." (PMID 33544155, 2021). "A more recent immunohistochemistry study of LRP1 expression, performed on infiltrating ductal breast carcinomas, brought different results as cytoplasmic LRP1 overexpression was identified in tumor cells in addition to non-neoplastic stromal cells, whereas normal ductal cells were always negative." (PMID 32850302, 2020). "The profile of LRP1 expression reflects the heterogeneity of human breast cancers." (PMID 26846992, 2016). "While, other studies argued that high LRP1 expression promotes breast cancer cell invasiveness, and LRP1 neutralization could abrogate cell motility in both tumor and nontumor cells despite the increased pericellular proteolytic activities of MMP2 and uPA." (PMID 22427881, 2012). "To exclude that differences of LRP-1 shedding levels that we observed between the two breast cancer cell lines could be attributed to modulations of LRP-1, MT1-MMP and/or ADAM-12, its main sheddases, we tested the effect of MβCD treatment on the expression of these three molecules." (PMID 26903870, 2016). "Therefore, we can hypothesize that cathepsin D enhances migration/invasion of breast cancer cells via LRP1 signaling." (PMID 22439866, 2012). "Similarly, Lrp1 is involved with breast cancer cell migration, DNA damage, and obesity." (PMID 20435547, 2010). "That is, the intracellular domain of LRP1 (LRP1-ICD) translocates to the nucleus, where it interacts with transcriptional regulators to repress the expression of ISGs in breast cancer cells." (PMID 39872986, 2025). "This engineered peptide selectively targets lipoprotein receptor-related protein 1 (LRP1), a receptor overexpressed on both BBB endothelial cells and brain-metastatic breast cancer cells." (PMID 41219968, 2025). "The intricate interplay of TBXAS1 and LRP1 influences cancer gene expression, while TBXAS1’s elevated levels in poor-prognosis breast cancer samples suggests a parallel lung cancer implications for LUSC." (PMID 38389572, 2024). "To further clarify the relationship between TM expression level and curcumin resistance, we investigated the gene expression level of several drug-resistant genes such as LRP1, MDR1, ABCC1, and MRP5 after curcumin treatment in ER+ breast cancer cells." (PMID 37239055, 2023). "In conclusion, our results demonstrated that TM plays a suppressive role in the progression and metastasis of ER+ breast cancer, and it regulates curcumin sensitivity by interfering with ABCC1, LRP1, and MDR1 gene expression." (PMID 37239055, 2023). "According to our data, silencing TM expression would alter acquired drug resistance based on LRP1 and MDR1 expression levels upon curcumin treatment in ER+ breast cancer cells." (PMID 37239055, 2023). "HSP90α, by binding to LRP1 and activating ERK and AKT pathways, induce migration and invasion in breast cancer cells." (PMID 33544155, 2021). "One study showed that the binding of the serine protease inhibitor protease nexin-1 (PN-1) to LRP1 stimulates MMP-9 expression, thereby promoting metastasis of breast cancer." (PMID 26738504, 2016). "The analysis of the breast cancer GWAS with the same non-cancer multi-tissue network resulted in one Bonferroni significant gene LRP1 (p-values 1.22 × 10− 6)." (PMID 39010058, 2024).
breast carcinoma (continued). "In our study, we showed that the MCF-7 human breast cancer cells resistant to Dox expressed a high level of LRP-1 as compared to that of parental non-resistant cells." (PMID 37768946, 2023). "Pro-cath-D interacts with LRP1 on the fibroblast surface, altering TME in breast cancers." (PMID 37124542, 2023). "Similarly, another highly related breast cancer cell line, MDA-MB-468, has an undetectable level of LRP-1 and yet a much higher level of inactive EGFR7." (PMID 35835845, 2022). "Using RNA-sequencing (Xentech biotechnology), we analyzed the quantity and the sequences of LRP-1 RNA in xenograft (PDX) derived from 20 breast cancer patients, including 12 TNBC and 8 non-TNBC (seven luminal and one HER2+)." (PMID 34680548, 2021). "Here, we show by using biophysical, biochemical, and cellular imaging approaches that efficient extraction of cell cholesterol and increased LRP-1 shedding occur in MDA-MB-231 breast cancer cells but not in MDA-MB-435 cells." (PMID 26903870, 2016). "Although no mutation in the LRP‐1 (TβR‐V) gene has been found related to cancer initiation or progression, the T allele of the C766 T polymorphism in the LRP‐1 (TβR‐V) gene is associated with an increased risk of breast cancer." (PMID 34485840, 2021). "Finally, we compared four distinct human breast cancer or normal control cell lines, MDA-MB-231 (Hsp90α secretion+ and LRP1+), HBL-100 (Hsp90α secretion− and LRP1+), HS-578T (Hsp90α secretion− and LRP1+) and T47D (Hsp90α secretion+ and LRP1+)." (PMID 26846992, 2016). "Consistent with our findings, increased expression of PAI-1 by the tumor stroma correlates with poor prognosis in ESCC and breast cancer patients, but no reports have evaluated the immunohistochemical expression intensity of both PAI-1 and LRP1 in tumor tissues." (PMID 33311557, 2021).
glioblastoma (45 papers, 2011 to 2025). The most malignant astrocytic tumor (WHO grade IV). "LRP-1 has been shown to be highly expressed in glioblastoma cells and glioblastoma-associated endothelial cells." (PMID 33918106, 2021). "In human U87 glioblastoma cell lines, hypoxia and serum deprivation were associated with statistically significant two-fold increases in LRP1 protein expression." (PMID 22027709, 2011). "Angiopep-2 also has a high affinity to LRP-1, which is usually more highly expressed in glioblastoma (GBM) cells and brain endothelial cells (BECs)." (PMID 40214585, 2025). "Angiopep-2 (TFFYGGSRGKRNNFKTEEY) is a peptide ligand of low-density lipoprotein receptor-related protein-1 (LRP1), which can cross the blood–brain barrier via receptor-mediated transcytosis and simultaneously target glioblastomas." (PMID 38339141, 2024). "LRP1 is highly expressed on the endothelial cells of the blood–brain barrier, and is also overexpressed on certain types of tumor cells (e.g., glioblastomas)." (PMID 36834514, 2023). "Low-density lipoprotein receptor-related protein 1 (LRP1) is expressed at high levels on the endothelial cells of brain capillaries and glioblastoma cells, but it is expressed at low levels in the normal brain parenchyma." (PMID 33482822, 2021). "LRP1 has also been shown to be overexpressed on glioblastoma cells, giving ANG2 tumor-specific targeting capabilities." (PMID 32582530, 2020). "The roles of LRP1 in cancer cells have been widely investigated in some cancer cell lines such as glioblastoma and thyroid cancer cell line." (PMID 32245111, 2020). "In glioblastoma cells, LRP1 was reported to regulate the expression of MMP-2 and MMP-9, which are responsible for promoting the migration and invasion of the cells." (PMID 32245111, 2020). "When we compared glioblastomas that expressed LRP1 mRNA in the top 10% with tumors that expressed LRP1 in the bottom 10%, increased LRP1 expression was significantly correlated with decreased patient survival (p = 0.026, n = 106)." (PMID 29088295, 2017). "Recently, the knockdown of LRP-1 expression in human glioblastoma U87 cells revealed that LRP-1 promoted cell migration and invasion by inducing the expression of MMP-2 and MMP-9." (PMID 23936774, 2013). "Here, using for the first time an LRP1 model that expresses high levels of LRP1, we characterised the uptake of [125I]-Angiopep-2 into U87 human glioblastoma cells as a function of time in the presence of 0, 1, 10, or 100 μM unlabelled Angiopep-2." (PMID 22027709, 2011). "We found that glioblastoma cell lines exposed to hypoxic or serum-deprived conditions upregulated LRP1 expression and exhibited significantly increased uptake of Angiopep-2." (PMID 22027709, 2011). "The enhanced transport capacity observed in this study was likely attributable to the presence of high LRP1 levels in individual glioblastoma cells." (PMID 22027709, 2011). "In addition, the expression and function of receptor low-density lipoprotein receptor-related protein-1 (LRP-1) was shown to correlate with glioblastoma cell invasion." (PMID 36430705, 2022). "Since LRP-1 is a substrate of MT1-MMP, we specifically questioned here how the MT1-MMP-to-LRP-1 cell surface expression ratio might regulate in vitro LRP-1-mediated An2 internalization within a human glioblastoma cell model." (PMID 36430705, 2022). "Based on these features, LRP1 might enable therapeutic agents to enter the central nervous system through the blood–brain barrier and become a potential therapeutic target for glioblastoma." (PMID 33482822, 2021). "In their study, knockdown of LRP1 using LRP1 small interfering RNA in the human glioblastoma cell line U87 led to a decrease in cell migration and invasion, which suggests that the expression level of LRP1 is associated with migration and invasion capabilities of these cancer cells." (PMID 26738504, 2016).
glioblastoma (continued). "This partitioning is most likely attributable to the presence of high LRP1 levels in individual glioblastoma cells, but may also reflect microenvironmental conditions near aggressive tumours and their influence over LRP1." (PMID 22027709, 2011). "The angiopep-2 peptide (TFFYGGSRGKRNNFKTEEY) is a ligand that binds to low-density lipoprotein receptor-related protein-1 (LRP-1), which is highly expressed on both BBB endothelial cells and glioblastoma (GBM) cells." (PMID 40006568, 2025). "LRP-1 is highly expressed on BBB endothelial cells and glioblastoma cells that allow nanocapsules to cross the BBB and to efficiently undertake the intracellular delivery to GBM cells." (PMID 39685907, 2024). "Due to the high expression in glioblastoma and BBB vascular endothelial cells, angiopep-2/LRP1 focus on glioblastoma treatment and therapy." (PMID 37122851, 2023). "Before confirming the feasibility of receptor-mediated delivery in vitro, the cellular cytotoxicity of RCD with and without oligomer, ligand–PEG, and PEG-modification was evaluated in human glioblastoma U87MG cells, which express LRP1 at a high level." (PMID 37896282, 2023). "Angiopep-2 (TFFYGGSRGKRNNFKTEEY) is a peptide ligand of low-density lipoprotein receptor-related protein-1 (LRP1), which can cross the BBB via receptor-mediated transcytosis and simultaneously target glioblastomas." (PMID 36834514, 2023). "More interestingly, Gopal showed a novel crosstalk mechanism involving the eHsp90α-LRP1 dependent regulation of EphA2 function, in which the eHsp90α-LRP1 signalling axis regulates AKT signalling and EphA2 activation during glioblastoma cell invasion." (PMID 35883467, 2022). "In line with this, in glioblastoma (GBM) cells, hypoxia not only amplifies eHSP90α secretion and its signalling, but also enhances LRP1 expression resulting in a positive loop that fuels cancer survival and progression." (PMID 33544155, 2021). "The low-density lipoprotein receptor related protein 1 (LRP1) is an endocytic receptor expressed in several tissues including the BBB cells and glioblastoma cells, and is known to mediate ligand transport across the endothelial cell layer of the BBB." (PMID 31617104, 2019). "Using U87MG glioblastoma cells expressing LTR-driven luciferase, we determined the extent to which LRP1 as well as ApoE2, ApoE3, and ApoE4 affected Tat-mediated HIV-1 LTR transactivation." (PMID 29558961, 2018). "The CXCR3 and LRP1 interaction was also evidenced in vivo in U87-CXCR3-A CAM tumors and in patient-derived glioblastoma cells." (PMID 29146996, 2017). "Taken together, the data as a whole argue strongly that LRP1-mediated endocytosis is a primary mechanism by which Angiopep-2 and ANG1005 enter glioblastoma cells." (PMID 22027709, 2011). "In combination, the inhibition and siRNA studies provide strong evidence that LRP1-mediated endocytosis is a primary mechanism by which Angiopep-2 and ANG1005 enter glioblastoma cells." (PMID 22027709, 2011). "Decreasing LRP1 activity, by RNA silencing or LRP1 competitors, decreased uptake of ANG1005 and Angiopep-2 into U87 glioblastoma cells." (PMID 22027709, 2011). "Low-density lipoprotein receptor-related protein-1 (LRP1) is expressed on the BBB and overexpressed in glioblastoma, which makes it the most used receptor for penetrating the BBB in drug development for the treatment of brain diseases and becomes an ideal treatment for brain cancer." (PMID 34425832, 2021). "LRP1 is abundant in many cancer cells and plays roles in oncogenesis, tumour progression and metastasis; ANG has been reported to enhance brain delivery of paclitaxel, increasing the survival time of glioblastoma-bearing mice." (PMID 26809004, 2016). "To address whether this microenvironmental conditioning had a role in our observations, we examined how LRP1 expression and ANG1005 endocytosis in glioblastoma cells were affected by conditions known to be present in aggressive tumours." (PMID 22027709, 2011).
glioblastoma (continued). "Prior studies showed that ANG1005 has a similar cytotoxic effect in vitro in U87 human glioblastoma cells as unconjugated paclitaxel, but those studies did not directly examine whether ANG1005 and Angiopep-2 entered cells by an LRP1-mediated mechanism." (PMID 22027709, 2011). "To further explore the implications of this increased LRP1 expression on endocytosis of Angiopep-2 and ANG1005, we examined human U87 glioblastoma cells and found that the changes in mRNA and protein expression were associated with ∼100% increased uptake of Angiopep-2 and ANG1005." (PMID 22027709, 2011). "In addition, transferrin receptors and LRP-1 are upregulated in dysfunctional the BBB in glioblastoma, and conjugated NPs targeting these receptors have been developed for enhanced drug delivery in glioblastoma cell lines and orthotopic mouse models." (PMID 38794182, 2024). "In parallel, LRP-1 protein expression was compared between adult U87 glioblastoma cells and pediatric DAOY medulloblastoma cells and was found expressed as much as in a sample of brain tumor tissue homogenate, whereas DAOY cells expressed very low levels of LRP-1." (PMID 36430705, 2022). "When survival of glioblastoma patients was examined in isolation, using the same dataset, LRP1 mRNA expression failed to be significantly correlated with patient survival, although there was a trend in which increased LRP1 mRNA was associated with decreased patient survival." (PMID 29088295, 2017). "Third, ANG1005 was transported into U87 human glioblastoma cells via a saturable receptor-mediated process that was inhibited by adding RAP, a known LRP1 ligand that competitively inhibits uptake of Angiopep-2 in brain capillary cells, or by reducing LRP1 expression using siRNA." (PMID 22027709, 2011).
migraine (45 papers, 2011 to 2026). "Advances in genome-wide association studies have revealed that LRP1 SNPs are associated with several diseases, including coronary heart disease, abdominal aortic aneurysm, and migraines." (PMID 38950861, 2024). "LRP1 SNPs are associated with several diseases and conditions such as migraines, aortic aneurysms, cardiopulmonary dysfunction, corneal clouding, and bone dysmorphology and mineral density." (PMID 38950861, 2024). "Multitrait colocalization analyses pointed at rs11172113 as the most likely causal variant in LRP1 for fibromuscular dysplasia, migraine, pulse pressure, and spontaneous coronary artery dissection." (PMID 39355906, 2024). "Genome-wide analyses have shown that a locus for the LDL receptor related protein 1 (LRP1) gene is most strongly associated with migraine disease." (PMID 35906498, 2023). "In conclusion, this present meta-analysis showed that the ACE-DD variant and ESR1-PvuII showed a significant risk of migraine in the Indian population in contrast to LRP1- rs11172113 which showed a protective role in the respective population." (PMID 37925562, 2023). "LRP1, for instance, is associated with the integrity of the arterial vessel wall and is the gene most highly correlated with migraine disease." (PMID 35906498, 2023). "Exome sequencing revealed that she had three rare variants in migraine genes, LRP1 c.13471G>C (p.(Asp4491His)), ECM1 c.1126T>C (p.(Cys376Arg)), and CARF c.1718C>T (p.(Ser573Phe))." (PMID 37107589, 2023). "Concerning the LRP1- rs11172113, the present review observed a protective role of variant (allelic model) with overall migraine, and such protective effect was found consistent with both of its clinical subtypes." (PMID 37925562, 2023). "Genetic variation in the LRP1 gene was associated with acute aortic dissection, cervical artery dissection and migraine." (PMID 35050224, 2022). "A GWAS of broadly defined headache using the UK Biobank data found significant associations at 28 loci, of which 14 overlapped with migraine, including the rs11172113 in the LRP1 as the top SNP." (PMID 31226929, 2019). "A GWAS meta-analysis of 375,000 patients involving 22 centers has identified 38 genetic susceptibility loci for migraine with the LRP1 region in chromosome 12 being the most strongly associated." (PMID 29397368, 2018). "Two SNPs, rs2274316 (MEF2D) and rs11172113 (LRP1), showed a significant association with high migraine attack frequency." (PMID 28656458, 2017). "GWAS supported that genetic variants (rs1835740 at 8q22.1 and rs11172113 in LRP1)associated with migraine, and both of these tow genetic variants were involved in the regulation of glutamatergic system." (PMID 26800698, 2015). "In another population-based genome-wide analysis including 5122 migraineurs and 18108 non-migraineurs individuals, rs2651899 (1p36.32, PRDM16) rs10166942 (2q37.1, TRPM8) and rs11172113 (12q13.3, LRP1) were among the top markers associated with migraine." (PMID 22379397, 2011). "In addition, a rare variant, c.13169A>C (p.(Asn4390Thr)), was identified within the migraine-associated gene LRP1 and was deemed pathogenic by the bioinformatic predictor fathmmMKL." (PMID 37107589, 2023). "Overall, the results of this meta-analysis indicated that the ACE-DD variant and the ESR1-PvuII were associated with an increased risk of migraine in the Indian community, while the LRP1-rs11172113 variant was associated with protection from migraine in this population." (PMID 37925562, 2023). "The LRP1 variant was selected for our study as it was associated with a broad spectrum of vascular pathologies, including cervical artery dissection, fibromuscular dysplasia, migraine and aortic aneurysms." (PMID 35050224, 2022). "For example, association of the minor C allele for the PRDM16 polymorphism rs2651899 was replicated in Swedish, Spanish and Han Chinese cohorts, while rs2651899 and LRP1 rs11172113 showed a protective effect on migraine susceptibility in a North Indian population." (PMID 31226929, 2019).